PACRG (parkin coregulated)
Description:
Microtubule inner protein (MIP) part of the dynein-decorated doublet microtubules (DMTs) in cilia axoneme, which is required for motile cilia beating. Suppresses cell death induced by accumulation of unfolded Pael receptor (Pael-R, a substrate of Parkin). Facilitates the formation of inclusions consisting of Pael-R, molecular chaperones, protein degradation molecules and itself when proteasome is inhibited. May play an important role in the formation of Lewy bodies and protection of dopaminergic neurons against Parkinson disease.
Synonyms: GLUP; PARK2CRG; FLJ32724; HAK005771; BUG21; pf12; PACRG2.1
Tractability: Small molecule: a structure with a bound ligand is known. PROTAC: ubiquitination databases record sites on it.
Gene: Protein-coding gene on chromosome 6 (162,727,132 to 163,315,500, forward strand). Ensembl gene ENSG00000112530.
Subcellular location: Cytoplasm, cytoskeleton, cilium axoneme; Cytoplasm, cytoskeleton, flagellum axoneme
Subcellular location (Human Protein Atlas): End piece; Mid piece; Principal piece; Mitochondria
Gene Ontology:
Molecular function: actin binding; alpha-tubulin binding; beta-tubulin binding; G protein-coupled receptor binding; heat shock protein binding; Hsp70 protein binding; Hsp90 protein binding; protein binding; protein-folding chaperone binding; ubiquitin protein ligase binding
Biological process: cellular response to unfolded protein; flagellated sperm motility
Cellular component: axonemal microtubule; cytosol; neuron projection; nucleus; sperm end piece; sperm midpiece; sperm principal piece; vesicle; axonemal B tubule inner sheath; axoneme; cell body; cilium; manchette; sperm flagellum
Genetic constraint (gnomAD): Loss-of-function variants: 29 observed, 30.4 expected, observed/expected ratio (o/e) 0.95, 90% interval 0.71 to 1.3. The upper end of that interval is the gene's LOEUF score, 1.3, which puts it in group 5 of 6, group 1 being the genes least tolerant of losing a copy. Missense variants: 279 observed, 331.83 expected, observed/expected ratio (o/e) 0.84, 90% interval 0.76 to 0.93. Synonymous variants: 116 observed, 124.14 expected, observed/expected ratio (o/e) 0.93, 90% interval 0.8 to 1.09.
Homologues: Orthologues: chimpanzee PACRG (100% identical), macaque PACRG (99% identical), dog PACRG (98% identical), pig PACRG (97% identical), rabbit PACRG (96% identical), rat Pacrg (96% identical), guinea pig PACRG (91% identical), mouse Pacrg (86% identical), tropical clawed frog pacrg (79% identical), zebrafish pacrg (77% identical), Drosophila melanogaster CG15120 (47% identical), Drosophila melanogaster CG17349 (37% identical), and 1 more. Paralogues in human: PACRGL (25% identical).
Diseases named in the same sentence as PACRG in open-access papers:
PACRG is named in the same sentence as 29 diseases in open-access papers, as found by Europe PMC text mining. Sharing a sentence is not in itself a finding about the gene and the disease. The quoted sentences say what the papers report.
leprosy (10 papers, 2012 to 2024). Leprosy is a chronic infectious disease affecting primarily the skin and peripheral nervous system. "Lastly, the PACRG gene, linked with Parkinson’s disease and increased susceptibility to leprosy, was identified." (PMID 38183082, 2024). "The present study fine mapped the overlapping PARK2 and PACRG gene regulatory region to detect the variant(s) associated with Leprosy susceptibility in geographically distinct and unrelated Indian population groups." (PMID 23861666, 2013). "The involvement of the PARK2 and PACRG genes with leprosy susceptibility in two distinct populations of the world, Vietnamese and Brazilian, and its non-replication in other populations suggests unravelling the reasons of heterogeneity between different population groups." (PMID 23861666, 2013). "Summary of associations between genes of innate immune response TLR, NOD2, PARK2, PACRG, and leprosy." (PMID 26793196, 2015). "Here, we investigated whether SNPs located in eleven genes: CCDC122/LACC1, IFNG, IL6, IL10, IL23R, LRRK2, NOD2, PACRG/PRKN, TLR1, TNF and TYK2 are associated to leprosy susceptibility in a population in the North of Brazil." (PMID 32433683, 2020). "In addition, polymorphisms of genes associated with Parkinson (Parkin—PARK2, parkin coregulated—PACRG and superoxide dismutase 2 -SOD2) and Alzheimer diseases (SOD2) modulate susceptibility to leprosy in independent populations." (PMID 30092084, 2018). "Various genes (HLA-DR, PARK2/PACRG, LTA, TLRs, etc.)and genomic regions (10p13, 6q25–26, 6p21, 17q11–q21, 20p13, etc.)of human genome have been associated with or linked to leprosy (or a particular clinical form of leprosy) by candidate gene association studies or genome-wide linkage analysis." (PMID 22238647, 2012).
Parkinson disease (8 papers, 2007 to 2024). A progressive degenerative disorder of the central nervous system characterized by loss of dopamine producing neurons in the substantia nigra and the presence of Lewy bodies in the substantia nigra and locus coeruleus. "PACRG (Parkin co-regulated gene) shares a bi-directional promoter with the Parkinson’s disease-associated gene Parkin, but the physiological roles of PACRG have not yet been fully elucidated." (PMID 33923444, 2021). "The study of Parkinson-related gene Parkin co-regulated gene (PACRG) showed that PACRG was strongly expressed in the choroid plexus of the lateral ventricle, third ventricle, and fourth ventricle in mouse brains." (PMID 36340696, 2022). "Parkin coregulated gene (PACRG) is co-expressed with Parkinson's disease-related Parkingene and shares a bidirectional promoter." (PMID 32271791, 2020). "An initially “unknown” gene identified with a TSS 200 bp upstream and divergent to the PARKIN gene (a ubiquitin E3 ligase determining aspects of parkinsonism), PACRG (PArkin Co-Regulated Gene;), was shown to share a common molecular pathway." (PMID 24261334, 2013). "This gene pair, consisting of the parkinsonism-related parkin gene (PARK2) and parkin co-regulated gene (PACRG) at chromosome 6q25.2-27, has many features in common with the PDCD10-SERPINI1 pair." (PMID 17212813, 2007).
asthenozoospermia (2 papers, 2021). "Mutations in the PACRG gene have been implicated in the etiology of human asthenozoospermia." (PMID 34572103, 2021). "Though the MEIG1/PACRG complex has not been implicated in male infertility, it is known that asthenozoospermia, or low sperm motility, is found in 80%, to varying degrees, of infertile men." (PMID 34673028, 2021).
asthma (2 papers, 2018 to 2019). "The impact of amino acid alterations in PACRG and RTTN proteins, and possible association of the sequence variants with asthma, is of uncertain significance, but their role in ciliary function may be of future interest." (PMID 30324028, 2018). "Although the effect of a V->M substitution is unknown, any change in PACRG structure or binding affinity could impact ciliary function, and may be of great interest in the context of severe asthma." (PMID 30324028, 2018).
ciliopathies (2 papers, 2022 to 2024). "In humans, several other proteins within or near the IJH—including PACRG—could similarly function in both motile and non-motile cilia, and thus potentially represent additional examples of proteins whose disruption break the dichotomy between motile and non-motile ciliopathies." (PMID 36329026, 2022).
clear-cell renal cell carcinomas (1 paper, 2017). "Among them, rs1408705 (with borderline significance, p = 0.00024) is located in PACRG (PARK2 co-regulated), which was previously found to be deleted in clear-cell renal cell carcinomas." (PMID 29190701, 2017).
Dyslipidemia (1 paper, 2025). "Dyslipidemia is a pivotal physiological mechanism associated with T2D, and it is plausible that this may represent the biological pathway through which PACRG manifests its DGEs." (PMID 39857704, 2025).
Hepatitis (1 paper, 2025). Inflammation of the liver. "Four interesting SNPs possibly associated with ICI-induced hepatitis were identified in our tumour specimens: three of them, GABRP rs11743438, GABRP rs11743735, and PACRG rs55733913 were found linked to a higher risk of hepatitis, while RGMA rs4778080 seemed to protect against this adverse event." (PMID 41153639, 2025).
hyperlipidaemia (1 paper, 2020). "We also revealed that the occurrence of PACRG A-T-A-T and a BMI > 24 kg/m2 or PRKN–PACRG C-G-T-G-T-T-C-A-T-C-T and a BMI > 24 kg/m2 was related to an increased risk of hyperlipidaemia in the subjects." (PMID 32747620, 2020).
nasopharyngeal carcinoma (1 paper, 2022). A carcinoma arising from the nasopharyngeal epithelium. "(2020) reported top three hub genes of PPI network of FANCI, POSTN, IFIH1, ZMYND10, PACRG and POU2AF1 for nasopharyngeal carcinoma biomarkers using STRING database PPI network construction with MCODE for module analysis." (PMID 36299526, 2022).
rheumatoid arthritis (1 paper, 2022). A chronic, systemic autoimmune disorder characterized by inflammation in the synovial membranes and articular surfaces. "Genes PACRG and VSTM1 were reported to be involved in the Parkinson and rheumatoid arthritis, respectively." (PMID 35568907, 2022).
schizophrenia (1 paper, 2021). A major psychotic disorder characterized by abnormalities in the perception or expression of reality. "In this study, the most strongly associated variant resides within an intron of the Parkin coregulated (PACRG) gene in schizophrenia patients with T2DM vs controls, and another variant that reached genome-wide significance resides within the intron of the TCF7L2 gene." (PMID 33315097, 2021).
tumour (5 papers, 2021 to 2025). "For the four newly discovered tumor suppressor genes, i.e., KCNIP4, CACNA1C, PACRG, and ST6GALNAC3, previous studies have proved their regulatory effect in tumors." (PMID 35321246, 2022). "Transcriptome and survival analyses revealed four potential tumor suppressor genes including KCNIP4, CACNA1C, PACRG, and ST6GALNAC3." (PMID 35321246, 2022). "Conversely, we found the previously identified PCa driver gene LRP1B (12/17) and new candidate genes TTC28 (16/27), CADM2 (12/16), LSAMP (11/16), EYS (16/18), PTPRD (12/18), PACRG (5/6) and PDE4D (12/17) to be predominately interrupted in tumours from African patients." (PMID 36045381, 2022). "As of PACRG, it is remarkable that this gene resides within the FRA6E CFS, where also the tumour suppressor PARK2 is located, suggesting that the deletion associated with this CFS may concomitantly disrupt PARK2 and increase the expression of PACRG, whose tumourigenic role remains largely unknown." (PMID 34187875, 2021).
cancer (3 papers, 2021 to 2024). A tumor composed of atypical neoplastic, often pleomorphic cells that invade other tissues. "Abnormal promoter methylation of PACRG, and ST6GALNAC3 were associated with downregulation of gene expression in cancers." (PMID 35321246, 2022).
PACRG also shares sentences with these, for which no sentence is quoted: infection (4 papers); Parkinson (4); malaria (2); male infertility (2); Alzheimer disease (1); autoimmune disease (1); cervical cancer (1); co-infection (1); colorectal cancer (1); diabetes (1); Hydrocephalus (1); infectious disease (1); infertile (1); retinitis pigmentosa (1); teratozoospermia (1).